TEAD2 (TEA domain transcription factor 2)
Diseases named in the same sentence as TEAD2 in open-access papers (continued):
Sharing a sentence is not in itself a finding about the gene and the disease.
cancer (16 papers, 2018 to 2025). A tumor composed of atypical neoplastic, often pleomorphic cells that invade other tissues. "The results showed that compared with the YAP-5SA group, the spherical forming ability, the number of spheroids and the expression level of proteins related to cancer stem cells in the si-TEAD2/4+YAP-5SA group were significantly decreased." (PMID 38553612, 2024). "A significant proportion of cancer patients carried the fusion- and frame-related mutations in YAP1 and TEAD2, respectively." (PMID 39572544, 2024). "Flufenamic acid, which binds the central pocket of the YAP-binding domain of TEAD2, inhibits the proliferation and migration of cancer cell." (PMID 31816819, 2019). "Even though the biological functions of TMEM140 and TEAD2 seem relevant in cancer development and progression, in D842V mutant GIST these proteins were found mutated in only one patient and therefore no definitive conclusion can be realistically drawn." (PMID 29510530, 2018). "In previous studies, TEAD2/4 affected the biological function of cancer cells, but its effect on CIN remains unknown." (PMID 38553612, 2024). "To identify genes whose expression is modulated by TEAD2 in CD4 T and B cells, we examined TEAD2 knockdown (KD) and over-expression (OE) in cancer cell lines (n = 8, respectively) from the Library of Integrated Network-Based Cellular Signatures (LINCS) Program." (PMID 35672799, 2022). "For example, TEAD2 is a transcription factor that regulates gene expression downstream of the hippo signaling pathway, a key regulator of cell proliferation that is frequently dysregulated in cancer." (PMID 33621242, 2021). "TEAD2 belongs to the protein family that may interact with transcription factors and may play a key role in cancer progression by regulating apoptosis and cell proliferation." (PMID 29510530, 2018). "Furthermore, results from large number of patients with CRC suggested that high expression of YAP1, TEA domain family member 2(TEAD2) and YAP1 target genes cysteine-rich angiogenic inducer 61 (CYR61) and ankyrin repeat domain 1 (ANKRD1) were associated with a high risk of cancer relapse." (PMID 32503256, 2020). "All these genes, except TEAD2/4, are known target of YAP/TAZ, involved in cancer progression and response to therapy." (PMID 38755629, 2024). "A pan-cancer differential TEADs expression identified a high expression of TEAD1, TEAD2, TEAD3, and TEAD4 in 3, 6, 5, and 12 types of cancer tissues, respectively." (PMID 38607003, 2024). "In particular, compared to the untreated group, the extract increased the expression of the tumor suppressor genes LATS2 and PTPN14 in HCT116 cells and decreased the expression of the oncogenes YAP1 and TEAD2 in HT29 cells, suggesting targeted modulation of cancer cell growth." (PMID 41516111, 2025). "The inclusion of a 12-nucleotide exon in TEAD2 (event ID: HsaEX0064372) is one of the most consistently decreased microexons in tumors (6/9 tissue types in our dataset) and is SRRM4 regulated, as evidenced by its up-regulation in all 6 cancer cell lines after SRRM4 overexpression." (PMID 33621242, 2021).
cardiovascular disease (1 paper, 2021). "In conclusion, TEAD2, TEAD4 and ZIC3 can increase the efficiency of reprogramming human urine cells into iPSCs, and provides a new stem cell sources for the clinical application and modeling of cardiovascular disease." (PMID 34448118, 2021).
TEAD2 also shares sentences with these, for which no sentence is quoted: infection (2 papers); melanoma (2); cholangiocarcinoma (1); duodenitis (1); gastritis (1); Hyperglycemia (1); hyperlipidemia (1); ischemic cardiomyopathies (1); kidney disease (1); mixed hyperlipidemia (1); pancreatic adenocarcinoma (1); pulmonary fibrosis (1); sarcoma (1); van Maldergem syndrome (1).